PLAUR (plasminogen activator, urokinase receptor)
Diseases named in the same sentence as PLAUR in open-access papers (continued):
Sharing a sentence is not in itself a finding about the gene and the disease.
Anxiety (3 papers, 2011 to 2021). Intense feelings of nervousness, tension, or panic often arise in response to interpersonal stresses. "Also, the suPAR gene (PLAUR) is found to be upregulated in visceral fat of non-obese participants with mood disturbances and/or anxiety." (PMID 34702245, 2021). "However, a small study found the suPAR gene (PLAUR) to be upregulated in visceral fat in non-obese patients with depression and/or anxiety." (PMID 34702245, 2021). "Post hoc comparisons revealed that non-obese patients diagnosed with anxiety or mood disorders (A/MD subgroup) had significantly higher mRNA levels of IL-1β (P < 0.01), IL-6 (P < 0.01) and PLAUR (P < 0.001 and P < 0.05, respectively) than non-obese patients without mental disorders (non-MD)." (PMID 30504920, 2018).
bladder urothelial carcinoma (3 papers, 2015 to 2024). "Elevated levels of urokinase-type plasminogen activator receptor (PLAUR) was detected in bladder urothelial carcinoma, showing a correlation with the abundance of 28 types of tumor-infiltrating lymphocytes." (PMID 38430429, 2024).
clear cell renal cell carcinoma (3 papers, 2014 to 2025). "Regarding PLAUR, small interfering RNA (siRNA)-mediated knockdown of PLAUR demonstrated notable inhibition of cell proliferation and migration in clear-cell renal cell carcinoma." (PMID 41154660, 2025).
colon adenocarcinoma (3 papers, 2012 to 2021). "Interestingly, one study examined colon adenocarcinoma biopsies, and saw laminin-5 positive staining was associated with budding cancer cells located at the tip of invading malignant epithelium, and that laminin-5 colocalized with PLAUR." (PMID 25079072, 2014).
mental disorder (3 papers, 2018 to 2025). A disease that has its basis in the disruption of mental process. "In addition to cytokines, both CCL2 and PLAUR mRNA levels were found to be higher in non-obese patients with mental disorders." (PMID 30504920, 2018).
pneumonia (3 papers, 2019 to 2023). An acute, acute and chronic, or chronic inflammation focally or diffusely affecting the lung parenchyma, caused by an infection in one or both of the lungs (by bacteria, viruses, fungi, or mycoplasma.). "PLAUR has been shown as one of the hub genes that strongly interact with other differentially expressed genes and reported as one of the key genes to be involved in Pneumonia caused by gram-positive bacteria." (PMID 34983375, 2022).
Airway obstruction (2 papers, 2009 to 2023). Obstruction of conducting airways of the lung. "It is also important to note that the current study examines the role of PLAUR SNPs in the development of airway obstruction in smokers and does not test the role of PLAUR polymorphisms in non smoking individuals." (PMID 19878584, 2009).
influenza (2 papers, 2017 to 2022). An acute viral infection of the respiratory tract, occurring in isolated cases, in epidemics, or in pandemics; it is caused by serologically different strains of viruses (influenzaviruses) designated A, B, and C, has a 3-day incubation period, and usually lasts for 3 to 10 days. "PLAUR plays a role in infiltration of immune cell is lung bacterial infection although didn’t show similar role in RSV and influenza using murine models." (PMID 28558071, 2017).
interstitial lung disease (2 papers, 2023 to 2025). A diverse group of lung diseases that affect the lung parenchyma. "Some recent studies found that PLAUR was essential in regulating dermatomyositis-interstitial lung disease by neutrophil-associated immune response." (PMID 36643579, 2023).
ischemic disease (2 papers, 2017 to 2022). Lack of blood supply to an area of the body, resulting in impairment of tissue oxygenation. "Conversely, rare, damaging variants of PLAUR were associated with lower risk of ischemic disease." (PMID 36194491, 2022).
ischemic heart disease (2 papers, 2018 to 2022). "Aggregate burden of rare damaging coding variants was associated with 41% lower odds of ischemic heart disease (95% CI 7%–63%), suggesting that heterozygous loss of function of variants of PLAUR are protective against ischemic heart disease." (PMID 36194491, 2022).
periodontitis (2 papers, 2022 to 2024). An acute or chronic inflammatory process that affects the tissues that surround and support the teeth. "Five genes (i.e., FMNL1, MANSC1, PLAUR, RNASE6, and TCIRG1) were identified as crosstalk biomarkers linking PD and periodontitis." (PMID 36545026, 2022). "The main findings of the current study identified five hub crosstalk genes (i.e., FMNL1, MANSC1, PLAUR, RNASE6, and TCIRG1) to be the linking mechanisms between periodontitis and PD." (PMID 36545026, 2022). "In periodontitis, MANSC1 was negatively correlated and the other four hub crosstalk genes (FMNL1, PLAUR, RNASE6, and TCIRG1) were positively correlated with five hub IRRGs, namely, AQP9, C5AR1, CD14, CSF3R, and PLAUR." (PMID 36545026, 2022).
peripheral artery disease (2 papers, 2020 to 2022). "Several genes were previously shown upregulated in circulating leukocytes in patients with peripheral artery disease (FCAR, FFAR2, DUSP5, PLAUR)." (PMID 31875423, 2020).
schizophrenia (2 papers, 2024). A major psychotic disorder characterized by abnormalities in the perception or expression of reality. "Also of note, a specific mutation in the PLAUR gene (rs4760), implicated in elevated levels of suPAR and has been associated with an increased risk of schizophrenia in males, converging with the sex-dependent increased risk of schizophrenia with heavy cannabis use." (PMID 39648682, 2024).
scleroderma (2 papers, 2012 to 2024). Scleroderma is a rare autoimmune connective tissue disorder characterized by abnormal hardening of the skin and, sometimes, other organs. "At the same time, our pre-venular capillaries and post-capillary venules contain key upregulated genes like PLAUR and SELE, respectively, that were dissimilar to those seen in SSc, signifying localized scleroderma has independent signatures and pathways distinct from SSc." (PMID 39408800, 2024).
seminoma (2 papers, 2010 to 2022). A radiosensitive malignant germ cell tumor found in the testis (especially undescended), and extragonadal sites (anterior mediastinum and pineal gland). "PLAUR also showed increased levels, by 6.2-fold, in human seminoma compared to normal testis." (PMID 35774118, 2022).
thyroid tumor (2 papers, 2010 to 2014). A benign or malignant neoplasm affecting the thyroid gland. "Some internal validations emerged, such as the pairs PLAU/PLAUR, SPP1/CD44, and SPP1/ITGA9, whose ligands have been demonstrated overexpressed in thyroid tumors as well as in our in vitro model." (PMID 20877637, 2010).
angioedema (1 paper, 2022). Swelling involving the deep dermis, subcutaneous, or submucosal tissues, representing localized edema. "Increased baseline PLAUR expression in HAE Type I patients compared with non‐HAE controls was associated with severe angioedema attacks (p = 0.0003)." (PMID 36254341, 2022).
atopic dermatitis (1 paper, 2021). "Notably, the transcriptional analysis of cultured lipid-raft-disrupted keratinocytes, whose transcriptional profiles most closely match lesional skin from atopic dermatitis (AD) patients, showed the upregulation of PLAUR expression." (PMID 33804792, 2021).
Brain atrophy (1 paper, 2012). Partial or complete wasting (loss) of brain tissue that was once present. "The inverse relationship we observe between soluble PLAUR and AD and brain atrophy is noteworthy and might suggest an inverse relationship either between soluble and, functional, membrane bound PLAUR or between central and peripheral PLAUR more generally." (PMID 23113945, 2012).
fungal infections (1 paper, 2022). "The data implies that PLAUR is likely to be involved in fungal infections as well." (PMID 34983375, 2022).
glaucoma (1 paper, 2020). Increased pressure in the eyeball due to obstruction of the outflow of aqueous humor. "Interestingly, we found 8 genes (FN1, THBS1, EPHB2, FGF2, DAB2, CD9, PLAUR and ITGA4) were crucial, suggesting that these genes might function as key factors in the pathogenesis of glaucoma." (PMID 31680442, 2020).
human papillomavirus infection (1 paper, 2021). "Whereas, PLAUR and co-expressed genes enriched in human papillomavirus infection, salmonella infection, proteoglycans in cancer, and chemokine signaling pathway, etc.." (PMID 35087738, 2021).
Insulin resistance (1 paper, 2011). Increased resistance towards insulin, that is, diminished effectiveness of insulin in reducing blood glucose levels. "Other proteins known to be upregulated during insulin resistance by adipose tissue such as RANTES, MCP1, PLAUR, CXCL5, were found in our studies to be upregulated in both adipose- and liver tissues." (PMID 21978410, 2011).
lactic acidosis (1 paper, 2008). Metabolic acidosis characterized by the accumulation of lactate in the body. "We further confirmed the induction of ERBB3, CD55, and PLAUR in response to lactic acidosis, and to the combination of hypoxia with lactic acidosis, via real-time PCR." (PMID 19057672, 2008). "Genes induced by lactic acidosis included: PLAUR, ERBB3, CD55, interleukin 15, CXCL16, angiogenin and MHC class I genes." (PMID 19057672, 2008).
mastitis (1 paper, 2018). Inflammation of breast tissue during lactation or postpartum due to an obstructed duct or infection. "For instance, PLAUR is involved in the regulation of inflammatory processes and has been found upregulated in the mammary gland cells infected with mastitis both in animals and in humans." (PMID 30271395, 2018). "On the other hand, our qRT-PCR analyses supported the downregulation of PLAUR and IFNGR1 and the upregulation of STC1 and IL19 in the breast milk SC from women with mastitis after treatment with the probiotic." (PMID 30271395, 2018).
Pleural effusion (1 paper, 2021). The presence of an excessive amount of fluid in the pleural cavity. "Although a splice variant of the PLAUR gene can generate a soluble uPAR construct, soluble uPAR is also generated by cleavage of cell-surface uPAR and occurs in serum and other biologic fluids, including pleural effusions." (PMID 33535429, 2021).
pleural mesothelioma (1 paper, 2021). A neoplasm that arises from the mesothelial cells of the pleura. "We collected the methylation profile of pleural mesothelioma, and found 8 novel interactors to be hypomethylated in pleural mesothelioma versus non-tumor pleural tissue, namely, ACVR1B, IL6, MGMT, NRG1, OAT, PHLDA2, PLAUR and TNC." (PMID 33916178, 2021).
sickle cell disease (1 paper, 2024). Sickle cell anemias are chronic hemolytic diseases that may induce three types of acute accidents: severe anemia, severe bacterial infections, and ischemic vasoocclusive accidents (VOA) caused by sickle-shaped red blood cells obstructing small blood vessels and capillaries. "Another pathway that could link increased PLAUR levels with coagulation activation is the association of this molecule with factor XII and neutrophil activation, which has been demonstrated in wound healing and sickle cell disease." (PMID 38803346, 2024).
speech dyspraxia (1 paper, 2019). "PLAUR is a target of FOXP2 too, but also an effector of SRPX2, another of FOXP2’s targets and a candidate for speech dyspraxia." (PMID 30971880, 2019).
tumor (595 papers, 1998 to 2026). "The PLAUR gene plays an important role in the progression of cancer and is highly expressed in tumors, where its expression is closely associated with tumor invasion and migration." (PMID 40561678, 2025). "A higher level of PLAUR has been reported in tumor-associated macrophages (TAMs) and other stromal cells in tumor microenvironments." (PMID 38396677, 2024). "The degree of methylation of the gene in ccRCC is also related to tumor progression, and the prognosis is better in patients with the low PLAUR expression caused by hypermethylation." (PMID 35675366, 2022). "The activation of plasminogen and extracellular matrix degradation mediated by PLAUR are important causes of tumor metastasis." (PMID 35675366, 2022). "As previously reported, PLAU and its receptor PLAUR were involved in regulating cell adhesion and promoting tumor cell migration, while c-Myc and AXL were associated with EMT, invasiveness, and migration." (PMID 35680853, 2022). "Coordination of tumor–ECM interactions, pericellular ECM proteolysis, and cell signaling underlies the critical role of PLAUR in tumor progression and survival." (PMID 35574375, 2022). "Overexpression of PLAU/PLAUR was found to be significantly associated with clinical variables including age, tumor type, WHO grade, histology, IDH-1 mutation, and 1p19q status." (PMID 35087738, 2021). "In cancer, aberrant expression of PLAU and PLAUR has been linked to tumor progression, metastasis, and shortened survival in cancer." (PMID 28881803, 2017). "In particular, PLAUR is a pan T cell activating antigen that has also been associated with epithelial-derived tumour development." (PMID 14612907, 2003). "PLAUR encodes the receptor for urokinase plasminogen activator and could be related to tumor growth and angiogenesis." (PMID 36212129, 2022). "The expression of PLAUR is linked to the invasion and migration of tumor cells 11-13." (PMID 35864968, 2022). "To further confirm that loss of uPAR led to the inhibition of tumor growth, we exploited “uPAR rescued expression” cell lines, previously obtained, briefly forcing the re-expression of uPAR by stably transfecting KO cells with a plasmid containing the sequence of PLAUR gene." (PMID 34055629, 2021). "Also a positive association between HER2 and PLAUR gene amplification (which was concordant with protein expression in both cases) was found in >90% of HER2-amplified individual tumor cells from the blood or tissue of patients with advanced recurrent BC." (PMID 25897424, 2015). "PLAUR, also known as urokinase-type plasminogen activator receptor, is a well-characterized receptor for matrix-degrading proteases that has been implicated in tumor cell invasion." (PMID 14737219, 2004). "In fact, SULF2 is involved in Wnt-driven tumor progression, PLAUR in extracellular matrix remodeling and migration, DUSP4 in sustaining epithelial–mesenchymal plasticity, and ATP6V0A4/V-ATPase-dependent acidification in invasive phenotypes." (PMID 41596301, 2026). "We mined TCGA using the GEPIA platform (Gene Expression Profiling Interactive Analysis RRID:SCR_018294) to compare the expression of PLAUR mRNA in PDAC tumor tissue versus adjacent normal tissue." (PMID 40759369, 2025). "This study further explored the role of PLAUR in tumor immunity by determining the correlation of PLAUR expression with immunological markers in NSCLC." (PMID 40561678, 2025). "In various in vivo tumor models, PLAUR inhibitor suppresses tumor growth and potentiates the efficacy of anti-programmed cell death protein 1 (PD-1) therapy." (PMID 40673864, 2025). "Studies have shown that PLAUR can promote tumor metastasis by mediating plasminogen activation and extracellular matrix degradation." (PMID 40474968, 2025). "The results of this study suggest that the PLAUR-mediated carcinogenesis of NSCLC involves tumor immune escape." (PMID 40561678, 2025).
tumor (continued). "PLAUR-expressing cancer cells also facilitate macrophages to infiltrate tumor mass, and macrophages can promote PLAUR expression in tumor cells in return." (PMID 38396677, 2024). "Single-cell data enable us to investigate the role of PLAUR in the MES phenotype in both tumor cells and immune cells." (PMID 38398231, 2024). "The EDI regulatory factor regulates invasion of cells, invasion of tumor, and microtubule dynamics through the PLAUR gene." (PMID 38711992, 2024). "In agreement with the biological features of the Inflammatory subtype, PLAUR expression was shown to correlate with the elevated inflammatory condition in the tumor." (PMID 38396677, 2024). "Results showed that the regulatory factors CRNDE, EDN1, JUNB, and MAP2K1/2, ZFP36 mainly regulate differentially expressed genes (VEGFA, EGFR, PLAUR) to regulate invasion of cells, invasion of tumor, and microtubule dynamics." (PMID 38711992, 2024). "Consistent with previous studies, microscopic images and statistical analysis revealed that the CM from macrophages enhanced the invasion of tumor spheroids, while silencing PLAUR partially inhibited this ability." (PMID 38398231, 2024). "These experiments confirmed that siRNA-mediated interference with PLAUR expression inhibits tumor migration significantly." (PMID 38398231, 2024). "We discovered a correlation between elevated PLAUR expression and tumor angiogenesis and inflammatory activities through a differential expression analysis." (PMID 38396677, 2024). "Bioluminescence measured at specific timepoints indicated that PLAUR knockdown attenuated tumor growth in mice." (PMID 38398231, 2024). "PLAUR plays a crucial role in extracellular matrix degradation and tissue remodeling, which regulates tumor invasion and metastasis, a pivotal characteristic of malignant tumors." (PMID 37153595, 2023). "PLAUR, or urokinase receptor, is instrumental in extracellular matrix remodeling, a process integral to tumor invasion and angiogenesis." (PMID 38137116, 2023). "Conversely, tumor-associated macrophages (TAM) expressed high levels of PLAU and PLAUR, and tumor-associated endothelial cells expressed high levels of PLAT, F2R and SERPINE1." (PMID 35053621, 2022). "To further clarify the influence of PLAUR expression on tumor immune cells, we conducted an expression correlation analysis between PLAUR expression and the biomarkers released by various infiltrating immune cells." (PMID 36052236, 2022). "According to the MEXPRESS database, the methylation of HNRNPAB/PLAUR/SEMA3A was associated with several clinical factors including ‘new tumour event after initial treatment’ and ‘tumour stage’." (PMID 36091160, 2022). "We examined the mRNA levels of six genes that constitute the «core» tumor coagulome: F3, PLAU, PLAT, PLAUR, F2R and SERPINE1 encoding TF, uPA, tPA, uPAR, PAR-1 and PAI-1, respectively, in tumors from TCGA." (PMID 35053621, 2022). "In this study, we collected the mRNA expression data of 33 tumor types, each derived from human patients obtained from TCGA database, and comprehensively analyzed the correlation between the expression of PLAUR in tumors and prognosis." (PMID 35675366, 2022). "In tumor tissues, PLAUR can activate extracellular matrix proteolytic enzymes outside the cells by binding to urokinase-type plasminogen activator (uPA or PLAU), its ligand." (PMID 35864968, 2022). "In paired tissues (normal = 57, tumour = 57), the expression of PLAUR was also significantly different (P < 0.01)." (PMID 36091160, 2022). "PLAUR was upregulated in GC, which promoted the malignancy of tumor cells, including anoikis resistance." (PMID 35864968, 2022). "Growing evidences indicate that down-regulation of PLAU and PLAUR attenuate the ability of tumor cells to invade and metastasize, but what triggers the regulation remains a critical question." (PMID 35087738, 2021).